CCL2 (C-C motif chemokine ligand 2)
Diseases named in the same sentence as CCL2 in open-access papers (continued):
Sharing a sentence is not in itself a finding about the gene and the disease.
breast cancer (continued). "Generally, constitutively high CCL2 expression levels existed in tumors, such as melanoma, ovarian, lung and breast cancer, but not all types of cancer 75-78." (PMID 32483450, 2020). "In parallel, CCL2 activities via CCR2, as well as CCL5-induced signaling were demonstrated to contribute to increased EMT and twist expression, at times accompanied by increased tumor cell invasion in breast cancer cells." (PMID 32582148, 2020). "Although CXCL12, CCL2, VEGF, MMP2, LOX, and CXCR4 were highly associated with HIF-1α expression, their prognostic significance in breast cancer is less so they were not chosen for further immunohistochemistry analyses." (PMID 33003428, 2020). "Thus, we detected the serum levels of S100A14, CCL2 and CXCL5 in our prospective cohort of 150 breast cancer patients and 125 healthy controls." (PMID 32483412, 2020). "The results showed that the levels of CCL2 and CCR2 were significantly higher in breast cancer patients, which could be used as a molecular marker for breast cancer diagnosis." (PMID 32253815, 2020). "Similarly, breast cancer-derived sEVs induce NFκB activation via TLR2 in macrophages resulting in upregulation of IL-6, TNF-α, G-CSF, and CCL2." (PMID 32015297, 2020). "Furthermore, the expression of PTEN can reduce the secretion of CCL2 and the expression of VEGF-A in macrophages, and inhibit the migration of breast cancer cells." (PMID 33224886, 2020). "As another mechanism to support CTCs survival, platelets secrete lysophophatidic acid (LPA) that binds to its receptors, LPAR1, 2 and on breast cancer cells and activates the secretion of IL6, IL8, CCL2 and CXCL1, enhance survival and increases the migration potential of CTCs." (PMID 33414786, 2020). "In breast cancer, high concentrations of TNF-α can activate receptors and trigger a potent and persistent activation of NFқB signaling, epithelial-to-mesenchymal transition, and continuous release of diverse chemokines, including CCL2 and CCL5." (PMID 31665136, 2019). "Our studies indicate that HTRA2 is important in CCL2/CCR2-mediated breast cancer cell growth and invasion, but not apoptosis." (PMID 31208996, 2019). "In summary, these data indicate that ALDH1A1 is important for CCL2/CCR2-mediated breast cancer cell growth, but not invasion." (PMID 31208996, 2019). "The subcellular localization of ANRIL and whether it correlates with IL6, CCL2, and POSTN expression, found in other conditions, in breast cancer is also unknown." (PMID 31572679, 2019). "Whether ANRIL expression correlates with IL6, CCL2, and POSTN in breast tumors was also investigated to provide evidence of how ANRIL may contribute to inflammation in breast cancer." (PMID 31572679, 2019). "SNAIL1 activates expression of CCL2, CCL5, IL-6, TNFα, and IL-8 in head and neck cancer cells and overexpression of SNAIL1 in 4T1 cells increased infiltration of M2-like macrophages and promoted metastasis in a breast cancer orthotopic model." (PMID 29593211, 2018). "(A-C) Boxplot representation of IL-6 (A) (Student’s t test, P < 2.2 × 10− 16), CCL2 (B) (Student’s t test, P < 2.2 × 10− 16), and MMP9 (C) (Student’s t test, P < 2.2 × 10− 16) expression levels in ER+/PR+ breast cancer compared to triple-negative breast cancer (TNBC)." (PMID 30458886, 2018). "Similarly to CCL2, CCL5 promotes the occurrence of deleterious TAMs and inhibits potential antitumor T cell activities, favoring the metastatic process of breast cancers." (PMID 30591657, 2018). "In line with this notion, immunohistochemical analysis of human breast cancer specimens shows that stromal but not tumoral CCL2 expression significantly correlates with macrophage infiltration, tumor size, and poor prognosis of patients." (PMID 30483271, 2018). "However, treatment of PyMT mice with the chemotherapeutic agent, doxorubicin, increases protein levels of CCR2 ligands CCL2 and CCL12 in the tumor stromal area, and promotes the recruitment of CCR2+ monocytes into the mammary tumors." (PMID 30483271, 2018).
breast cancer (continued). "Besides, HECTD3, PSMB10, UBD, UBE2C, and UBE2S involved in the ubiquitin proteasome pathway, as well as CCL2, CCR1, CXCL10, CXCL11, and IL2RG implicated in the cytokine–cytokine receptor interaction pathway, might be used for evaluating the efficacy of neoadjuvant chemotherapy in breast cancer." (PMID 29685151, 2018). "CCR4, whose ligands are CCL2, CCL3, CCL5, CCL17 and CCL22, is crucial for immune cell homeostasis but is also involved in hematologic malignancies, such as adult T-cell leukemia and Hodgkin’s lymphomas, and some solid tumors, including breast cancer." (PMID 30591657, 2018). "To date, there are no reports of the diagnostic usefulness of CCL2 and CCR2 serum or plasma levels in breast cancer patients." (PMID 30151375, 2018). "Recent studies have indicated that CCR2, but not CCL2, regulates CCL2-induced breast cancer cell survival and motility through MAPK- and Smad3-dependent mechanisms." (PMID 28424406, 2017). "Estrogen receptor (ER) negative breast cancers exhibit increased expression of inflammatory chemokines CCL2, CCL4, and CXCL8 compared to ER+ breast cancers and this correlates with the phenotype of the inflammatory infiltrate in the tumor." (PMID 28143493, 2017). "Importantly, intranasal delivery of CCL2 increased the recruitment of leukocytes into the BAL fluid and increased subsets of T cells in the lung, but enhanced the outgrowth of the 67NR breast cancer cells in the lung." (PMID 28143493, 2017). "Furthermore, we showed relative to normal breast tissue that elevated levels of CCL2, IL1B and OPG mRNA levels were detected in stage I breast cancer human tissue samples." (PMID 28143606, 2017). "Taking into account the correlation between OPG and CCL2 mRNA expression, we next examined whether macrophages can induce OPG secretion in breast cancer cells." (PMID 28143606, 2017). "However, among patients with luminal A breast cancer, the most abundant of the sub-group, RFS differences among patients with high and low CCL2 expression was equivocal (p = 0.1)." (PMID 28143493, 2017). "Moreover, linear regression analyses showed that higher Gpr132 expression was significantly correlated with higher expression of pro-inflammatory markers including CCL2 (MCP-1), MMP9 and PTGS2 (COX-2) in breast cancer lesions." (PMID 27692066, 2016). "CCL2 gene silencing but not CCL2 antibody neutralization, significantly reduced CCL2 expression in breast cancer cells over time." (PMID 27283985, 2016). "Therefore, we first determined the effect of CCL2 gene silencing on the numbers of CD24-/CD44+ cells, a well characterized breast cancer stem cell population." (PMID 27283985, 2016). "Rather than exerting its effects directly on mammary carcinoma cells by enhancing proliferation or survival as described in other models, CCL2 molds the tumor microenvironment to promote tumor progression." (PMID 27820834, 2016). "For example, both the MO chemokines CCL2 and CCL5 are overexpressed in breast cancer." (PMID 26155942, 2015). "CCL2 and CCL5 (RANTES) chemokines have been extensively studied in breast cancer." (PMID 25165728, 2014). "The outcome of such a process, if taking place in vivo in malignancies with high TNFα expression - as is the case in breast cancer - may be high production of pro-tumorigenic factors by the tumor cells, including angiogenic ones (such as CXCL8 and CCL2)." (PMID 24598028, 2014). "MCP-1, also referred to as CCL2, signals to increase macrophage infiltration into the inflamed mammary tissue, thereby increasing the number of deleterious TAM that accumulate in mammary tumor tissue." (PMID 25360510, 2014). "We have previously shown that splenic macrophages from mammary tumor-bearing mice secrete higher levels of the pro-angiogenic molecules CCL2, CXCL2, and MMP-9 (compared to non-tumor bearers) and that CHI3L1 stimulates this increased production." (PMID 24399973, 2013).
breast cancer (continued). "We also demonstrate that in vivo treatment with chitin microparticles, a substrate for CHI3L1, resulted in decreased production of CHI3L1, CCL2, CXCL2, and MMP-9 in BALF, and more specifically by interstitial and alveolar macrophages of mammary tumor-bearing mice." (PMID 24399973, 2013). "Plasma CCL2 levels were not correlated with pathological factors or subtypes of breast cancer." (PMID 39749673, 2025). "Then, CCL2 recruits monocytes to the lung and subsequently form a pulmonary PMN characterized by monocytes, high infiltration of macrophages, immunosuppression, and enhanced vascular permeability, ultimately accelerating the formation of breast cancer lung metastasis." (PMID 37534210, 2023). "Another research revealed that downregulating CCL2 expression could significantly reduce carcinogenesis and Notch1 expression in a xenograft model containing both fibroblasts and breast cancer cells." (PMID 38045829, 2023). "Other biomarkers like insulin, C-C motif chemokine ligand 2 (CCL2), transforming growth factor β 1(TGF-β1), and Treg-like molecule (Treg: Regulatory T cells) were also discussed in some of our reviewed publications, regarding their relevance primarily to breast cancer treatment." (PMID 37181043, 2023). "For instance, it was demonstrated that CCL2/monocyte chemoattractant protein-1, CCL5, IL-1β, IL-6, tumor necrosis factor α, vascular endothelial growth factor, and leptin released by CAAs in the TME promote the proliferation, and dissemination of breast cancer cells." (PMID 36980280, 2023). "Moreover, PTX-elicited extracellular vesicles contain high amount of annexin A6 (ANXA6), a Ca2+-binding protein, which can promote increased CCL2 expression in endothelial cells and consequent recruitment of inflammatory monocytes expressing CCR2, thereby promoting lung metastasis in breast cancer." (PMID 35280672, 2022). "Thus, in this model of breast cancer lung metastasis, IL4 potentiates an immunosuppressive Th2 environment through its actions on monocyte differentiation to MAMs after their recruitment via CCL2." (PMID 36077870, 2022). "During cancer progression, C-C motif chemokine ligand 2 (CCL2) and colony-stimulating factor 1 (CSF1) recruit and maintain macrophages in the TME, and CSF1-recruited TAMs express TFs, including Ets2, to promote angiogenesis, tumor growth, and breast cancer metastasis." (PMID 36248881, 2022). "Highly invasive human breast cancer cell lines (MDA-MB-231 and BT-549) were shown to express low levels of CCRL2, and overexpression of the receptor negatively affected the growth of these cells in vitro and in vivo, as well as their chemotactic response to CCL2 and invasive properties." (PMID 34638484, 2021). "The CC chemokine ligand (CCL2)-CCR2 axis is involved in multi-tyrosine kinase inhibition and microtubule inhibition resistance in the colon and prostate cancer cells, and CCR2 promotes cell growth and cell cycle progression via Src and Akt activation in breast cancer cells." (PMID 33406639, 2021). "Metastasis- and inflammation-associated microenvironmental factor S100A4 activates the basal-like subtype of breast cancer cells to trigger monocyte-to-macrophage (M2) differentiation and polarization, and elevates secretion of pro-inflammatory cytokines such as IL-8, IL-6, CXCL10, CCL2 and CCL5." (PMID 34283088, 2021). "In addition, CCL2 was shown to activate the STAT3 and NOTCH1 pathways and macrophages-derived chemokine CXCL8 increases CSCs-like populations and enhances mammosphere formation via activation of AKT/mTOR signaling in renal and breast cancer." (PMID 33414786, 2020). "In a mouse model of HER2+ breast cancer, researchers found that overexpression of HER2 could induce the production of CCL2 by cancer cells and that myeloid cells attract CD206+/Tie2+ macrophages that promote the epithelial to mesenchymal transition in HER2+ breast cancer cells." (PMID 31528210, 2019).
breast cancer (continued). "By understanding the molecular and cellular mechanisms of CCL2/CCR2 signaling facilitating growth and invasion of cancer cells, we may better understand the potential effects of CCL2 or CCR2 inhibitors on tumor progression, and design improved strategies for treatment of invasive breast cancer." (PMID 31208996, 2019). "CAAs secrete more chemokine (C–C motif) ligand 2 (CCL2), chemokine (C–C motif) ligand 5 (CCL5), interleukin-1β (IL-1β), interleukin-6 (IL-6), tumor necrosis factor-alpha (TNF-α), vascular endothelial growth factor (VEGF), leptin, etc., which can promote the invasion and metastasis of breast cancer." (PMID 31500658, 2019). "Therefore, CCL2, CCR1, CXCL10, CXCL11, and IL2RG might be involved in neoadjuvant chemotherapy in breast cancer via the cytokine–cytokine receptor interaction pathway." (PMID 29685151, 2018). "Interestingly, it has been shown that in vitro exposure of human monocytes to CCL2 results in the enrichment of the CD14+CD16+ cell subset and that this chemokine is responsible for inflammatory monocyte accumulation induced by breast cancer cell microenvironment." (PMID 29312324, 2017). "This conclusion is consistent with previously published data showing that FXYD5 overexpression in breast cancer cells induces the phosphorylation of AKT, which promotes the transcriptional activity of NF-κB-responsive promoter elements and increases levels of CCL2 mRNA." (PMID 28620381, 2017). "For example, CCL2 produced by breast cancer cells and stromal cells recruits CC chemokine receptor 2 (CCR2)-positive inflammatory monocytes to the lungs; then these inflammatory monocytes secrete vascular endothelial growth factor to promote breast cancer cell extravasation and lung metastasis." (PMID 28356139, 2017). "Here, we found the following: first, CCL2/CCR2 interaction promoted A549 cell proliferation, migration and invasion, although to a lesser extent compared with those in other cancer cells, such as prostate and breast cancer cells, which was indicative of tissue-specific functions for CCL2 signaling." (PMID 28424406, 2017). "There is a lack of articles discussing CCL2 and CXCL2 in the context of tumorigenesis of RCC; however, these chemokines were found to be associated with tumor growth and progression of melanoma and breast cancer." (PMID 28846693, 2017). "(However, since CCL2 may be produced by non-malignant stromal cells in mammary cancers in situ, this experiment does not rule out a direct effect of paracrine murine CCL2)." (PMID 27820834, 2016). "Similarly, antibody blockade of human CCL2 in a mouse xenograft model did not alter the growth of transplanted mammary tumors, suggesting that autocrine CCL2 does not contribute to tumor growth in this model." (PMID 27820834, 2016). "Therefore, we examined whether the presence of mammary carcinomas affects the development and deployment of CD45–CD117/c-Kit+Flk1/Vegfr2+ EPCs and whether CCL2 and CCR2 play a role." (PMID 27820834, 2016). "Additionally, although CCL2 was not correlated with pathological factors or cancer subtypes, it exhibited decreased levels posttreatment, suggesting that it is a potential prognostic marker for breast cancer." (PMID 39749673, 2025). "Thus, targeted neutralization of CCR2 or blockade of CCL2 inhibited the recruitment of TAMS and monocytic MDSC at tumor sites, angiogenesis, cancer development, and metastasis in various cancer models, among them breast cancer, lung cancer, ovarian cancer, and others." (PMID 34944943, 2021). "Another study also showed that genetic deletion of Ccl2 in the host (i.e., stromal) cells but not in cancer cells results in reduced TAM infiltration, deficient angiogenesis, and impaired tumor growth in mice that are orthotopically injected with 4T1 mammary tumor cells." (PMID 30483271, 2018).
breast cancer (continued). "Our data indicate the importance of evaluating CCR-2 expression in TEpCs as well as CCL-2 expression in TEpC and spindle-shaped stromal cells, because the pathways that produce CCR-2 and its ligands may provide targets for the prevention of breast cancer progression and metastasis." (PMID 28420351, 2017). "Previous analysis of serum from patients with breast cancer and cerebral metastases found increased levels of CX3CL1 and CXCL13 (levels of CCL2 among other chemokines were not elevated)." (PMID 37924145, 2023). "Collectively, these data strongly indicate that CCL2, rather than CXCL3, recruits MHCIIhi neutrophils to promote lung metastasis of breast cancer." (PMID 37563136, 2023). "CCL2 mRNA was also highly upregulated in A3250 cells not only in comparison to SUM149, but also to IBC3 and to a panel of non-IBC breast cancer cell lines." (PMID 34824220, 2021). "Namely, increased CCL2 level in the tumor by doxorubicin treatment promotes CCR2 dependent monocyte recruitment, although the PyMT mammary tumors normally recruit monocytes/macrophages via CCR6 but not CCR2." (PMID 26275794, 2015). "Next, we compared the three groups of breast cancer patients (DCIS, IDC-no-relapse, IDC-with-relapse) with respect to the incidence of expression of CCL2, CCL5, TNFα and IL-1β in the tumor cells." (PMID 21486440, 2011). "Although CD163+ MØs, CCL2 and CCL7 are associated with cancer metastasis and poor prognosis and high CCL2 levels are found in various cancer types, including breast cancer and some NSCLC31–33, blocking the CCL2/CCR2 axis alone does not impede tumors from recruiting monocyte-origin resident MØs5." (PMID 38076998, 2023). "This was in contrast with the expression of known HIF target genes involved in breast cancer metastasis not included in the hypoxia signatures (LOX, LOXL2, LOXL4, CCL2, L1CAM, ANGPT1, and ANGPT2), whose expression showed a positive correlation with the signatures." (PMID 29540773, 2018). "Although CCL18 induces the increased vimentin and decreased E-cadherin, as well as the upregulation of GM-CSF, IL-8, CCL2, and GRO, the upregulated levels of IL-8 in breast cancer cell might be not enough to induce the enrichment of cancer stem cell and mediate chemoresistance." (PMID 36418470, 2023). "In the EMT6.5 mammary tumor model, conventional radiotherapy (CRT) but not microbeam radiation therapy (MRT) induced a substantial increase in TAMs and TANs, and increased levels of CCL2 (which can be released by TANs to exert chemoattractant functions) were also observed in tumors subjected to CRT." (PMID 32849640, 2020). "The tumor-promoting activities of the inflammatory mediators CCL2 & CCL5 and TNFα & IL-1β in breast cancer are not fully overlapping (references above), therefore their coordinated expression may eventually provide advantage to the developing and metastasizing tumor." (PMID 21486440, 2011).